EGFR (epidermal growth factor receptor)
Diseases named in the same sentence as EGFR in open-access papers (continued):
Sharing a sentence is not in itself a finding about the gene and the disease.
tumor (continued). "This is based on the fact that targeted therapies are available for these patients (although not in the neoadjuvant setting), and that ALK‐/EGFR‐altered tumours have been shown to have a poor response to IO therapy, leading to their exclusion from the CheckMate 816 trial." (PMID 40911027, 2025). "Besides, it had a 76% reduction in tumor volume, significantly increased the antioxidant activity (SOD, CAT, GSH), decreased the levels of inflammatory biomarkers (IL-6, COX-2, NF-κB), and markedly downregulated the EGFR expression (p < 0.0001)." (PMID 41599143, 2025). "However, suppose TCEs are engineered with a modified design to specifically recognize EGFR on tumor cells and bind no or less EGFR on normal tissues." (PMID 40510353, 2025). "However, for the processing of clinical samples, GEM devices functionalized with either anti-EpCAM or anti-EGFR were used to ensure the capture of DTCs of varying surface markers since we do not know the true identity of tumor cells in clinical samples." (PMID 40073025, 2025). "Importantly, we have not observed on-target/off-tumor toxicities even when EGFR-LiTE is able to mediate T cell activation against murine EGFR." (PMID 41341587, 2025). "Engineered exosomes, such as GEMINI-Exos armed with anti-CD3, anti-EGFR, PD-1, and OX40L, have demonstrated significant inhibition of triple-negative breast cancer in mice, while surface modifications like PEGylation or CD47 overexpression enhance circulation and tumour targeting." (PMID 41181109, 2025). "Drug resistance may arise from various molecular mechanisms, such as abnormal activation of the epidermal growth factor receptor (EGFR) signaling cascade, dysregulation of the PI3K/AKT/mTOR pathway, and the role of immunosuppressive cells in the tumor microenvironment (TME)." (PMID 40688093, 2025). "Encouraged by the long‐term inhibitory effect of Gel@PCZ on EGFR endocytosis in vivo, we conducted in vivo experiments to determine whether the combined local delivery of PCZ and cetuximab (Gel@Cmab/PCZ) enhances tumor suppression compared with cetuximab alone (Gel@Cmab) or the free drug." (PMID 39560161, 2025). "Therefore, preclinical evaluation of rTBL-1 in CRC is relevant, regardless of the level of EGFR expression in the tumor." (PMID 40006027, 2025). "EGFR activates mTORC1 via the PI3K/AKT pathway, upregulating glutaminase (GLS) to fuel nucleotide synthesis, while STAT3-mediated cell cycle progression creates a self-reinforcing loop that provides both biosynthetic precursors and proliferative signals for rapid tumor growth." (PMID 40904507, 2025). "Additionally, MET-amplified EGFR-TKI-resistant cells induce CD73, which is responsible for producing the immunosuppressive metabolite adenosine and inhibiting the activation of STING, potentially promoting tumor progression." (PMID 38566036, 2024). "EGFR alterations with subsequent protein overexpression activate a plethora of signaling pathways, including PI3K/Akt and extracellular signal-regulated kinase (ERK1/2), which promote tumor proliferation, resistance to apoptosis, chemoradioresistance, and GBM tumor recurrence." (PMID 39001381, 2024). "Epidermal growth factor receptor (EGFR) × mesenchymal–epithelial transition factor (MET)‐targeting BsAb amivantamab, functions via blocking ligand‐induced activation and leads to internalization and degradation of Ab‐bound receptors, thereby inhibiting tumour cell proliferation." (PMID 38963257, 2024). "Our detection rate of activating EGFRm and EGFR T790M ctDNA in baseline pre-treatment plasma samples was in line with previous reports, supporting the use of plasma EGFRm and T790M testing when tumor biopsy is not possible." (PMID 38418463, 2024). "However, differences in tumor microenvironment changes dependent on the generation of EGFR TKI are not currently defined in the literature." (PMID 39483887, 2024).
tumor (continued). "In patients without tissue profiling EGFR ex19del, EGFR L858R and KRAS G12/G13 mutations were detected by ddPCR in two, one and ten patients, respectively, corresponding to 7.1% of all patients without NGS of tumour tissue." (PMID 39083479, 2024). "Furthermore, Bcl2 and Bcl2l2 expression in tumor cells were relatively low and not increased by EGFR-TKI treatment." (PMID 39122703, 2024). "In addition, TAMs also produce a variety of factors that directly stimulate tumor cell proliferation and motility, including FGF, hepatocyte growth factor (HGF), epidermal growth factor receptor (EGFR) family ligands, platelet-derived growth factor (PDGF) and TGF-β." (PMID 39606239, 2024). "However, the EGFR protein staining differences were not convincing enough regarding its potential influence on the pathological nature of this type of tumor." (PMID 38390896, 2024). "Thus, although genetic-driven tumour profiling is similar to that of IPF-free LC, as documented by EGFR behaviour and asset, the immune tumour status should be strictly related to the surrounding IPF stroma and the clinicopathologic features of the interstitial diseases." (PMID 39741973, 2024). "PFS was improved with EGFR-TKIs in combination with bevacizumab compared to EGFR-TKIs monotherapy, particularly in the NEJ026 trial and several others, suggesting improved PFS with bevacizumab is potentially due to increasing drug distribution and tumor-suppressive effects." (PMID 38539522, 2024). "Informed circulating tumor DNA (ctDNA) detection in EGFR-mutant NSCLC could help identify patients nonresponsive to neoadjuvant immunochemotherapy." (PMID 38897205, 2024). "The tumor’s location plays an important role in treatment decisions in mCRC, with left-sided tumors showing significant benefits from anti-EGFR mAbs, whereas right-sided tumors may not derive the same benefits in terms of PFS and OS." (PMID 38254903, 2024). "The tumor localization of [64Cu]Cu-NOTA-trastuzumab Fab-PEG24-EGF bsRICs in these tumors with heterogeneous receptor expression was evaluated by PET and biodistribution studies and compared to tumors formed of SK-OV-3 cells or MDA-MB-468 cells that homogeneously express HER2 or EGFR, respectively." (PMID 38711454, 2024). "In addition, within GBM tumors, some tumor cells are sensitive to EGFR inhibitors, while some cells are not." (PMID 38531616, 2024). "As EGFR and MUC1 were stained in consecutive sections with a thickness of 4 μm, which was smaller than the averaged diameter of tumor cells (7-20 μm in most cases), we could observe if they were co-expressed in the same tumor cells." (PMID 39664199, 2024). "Second, and in contrast, cetuximab and EGFR-targeted therapy has long been an approved treatment protocol for RAS wild-type, metastatic colorectal cancer, and SHP2 inhibitors reliant on phospholipase C gamma 1 (PLCg1) exhibit anti-tumor effects in cancer cells resistant to cetuximab." (PMID 38504984, 2024). "Moreover, STAP-2 knockdown-induced suppression of tumor cell growth was observed in EGFR-activated, but not in EGFR-inactivated states." (PMID 38745775, 2024). "Our study suggests that at least one such process may involve circumferential, rather than angiogenic, vascular growth (vasectasia) driven largely (perhaps not exclusively) by EV-mediated transfer of EGFR between tumour and endothelial cells." (PMID 38570528, 2024). "Our observations suggest a link between the expression of EGFR by the mesenchymal (but not proneural) subset of tumour-initiating GSCs and their ability to orchestrate formation of vascular patterns enriched in large intratumoural blood vessels and low overall vascular density." (PMID 38570528, 2024).
tumor (continued). "Therefore, we established intestinal tumor organoids using the intestinal polyps from the Apcmin mice and supplemented RSPO1 in the organoid culture medium to investigate the effect of ZNRF3/RNF43 deactivation on organoid growth and EGFR." (PMID 38260423, 2024). "Therefore, targeting autophagy may be a promising approach to improve the therapeutic efficacy of EGFR–TKIs in advanced NSCLC, which provides a new vision for reducing drug resistance of tumor-targeted therapy." (PMID 39090096, 2024). "Previous studies have reported that patients with LUAD EGFR‐negative tumors show a higher response to ICIs,12 which may be largely determined by the complex tumor immune microenvironment (TME) in LUAD." (PMID 38886907, 2024). "In this manuscript, we reported the generation of EGFR- and HER2-targeting T-BsAbs, as well as a heterodimeric EGFRxHER2 T-BsAb, capable of driving T cell infiltration and eliciting impressive in vivo anti-tumor potency against established cell-derived and patient-derived PDAC xenografts." (PMID 38650005, 2024). "The limitation of this study is the simplified cellular system, which allows focusing on the transactivation of HER2 by EGFR without having to consider additional crosstalk from the tumor microenvironment (TME), circulating growth factors, and the diverse functions of the immune system." (PMID 38892166, 2024). "The compensatory upregulation of molecular target structures, such as EGFR or IGF1R, for example, leads to reduced sensitivity to erlotinib (EGFR inhibitor) or substances targeting the VEGF signaling pathway (IGF1R contributes to tumor angiogenesis through upregulation of VEGF)." (PMID 38730642, 2024). "Fascinatingly, this finding suggests that EGFR may not be AREG’s sole surface receptor within the tumor immune microenvironment." (PMID 38831884, 2024). "M2-type macrophages then secrete epidermal growth factor receptor (EGFR), transforming growth factor-β (TGF-β), vascular endothelial growth factor (VEGF), platelet-derived growth factor (PDGF), IL-10, IL-6 and arginase-1, promoting tumor angiogenesis and tumor progression." (PMID 38792234, 2024). "However, unlike other tumour types where inhibition of wild-type EGFR by monoclonal antibodies or tyrosine kinase inhibitors (TKIs) is beneficial, EGFR-targeted therapies in TNBCs have shown variable and unpredictable clinical responses (1.7% to 38.7%)." (PMID 38605363, 2024). "Although not performed routinely, immunohistochemistry for tumor PD-L1 and EGFR expression may predict whether a patient benefits from targeted systemic therapies, such as immunotherapies and anti-EGFR (primarily cetuximuab) treatments." (PMID 38769503, 2024). "Future studies need to investigate the role of ANTXR1 expression in other pathways like EGFR, the complement and coagulation cascades, as well as metastatic pathways including the potential role of TEM8 in the EMT process (with uPA and transgelin), and its importance in tumor biology." (PMID 39917181, 2024). "Specifically, for tumor cell targeting we used the CL4 2′Fluoro-pyrimidines (2′F-Py) RNA aptamer (Kd, 10 nM; 39 nt), capable of binding at high efficacy to the extracellular domain of epidermal growth factor receptor (EGFR), one of the most potent oncoprotein of human cancer." (PMID 38532439, 2024). "Analysis of the residual malignant tumor cells revealed notably higher CD73 expression in the highly resistant subgroup and extensive TACSTD2 (TROP2) expression, which would also enlighten the study design of an ADC combination strategy as a perioperative setting for EGFR-mutant NSCLC." (PMID 38897205, 2024). "Indeed, a recent phase I clinical trial in six patients with multifocal recurrent GBM showed that the intrathecal injection of bivalent CAR-T cells targeting both IL-13Rα2 and EGFR led to tumor reduction in all patients, although none met the criteria for ORR." (PMID 39406966, 2024).
tumor (continued). "ALK‐ and EGFR‐positive NSCLCs have distinct histological profiles, suggesting that their tumor marker profiles may also be different; however, no study to date has compared the tumor marker profile of NSCLCs with different driver gene mutations." (PMID 38400801, 2024). "In patients with NSCLC, pembrolizumab, an anti–PD-1 therapy, in the first-line setting showed superior efficacy compared with PDC in those patients who had PD-L1 expression in > = 50% of viable tumor cells without epidermal growth factor receptor (EGFR)/anaplastic lymphoma kinase (ALK) aberrations." (PMID 39448966, 2024). "Furthermore, a 2007 study assessed the ability of a statistical model to analyze protein expression levels of EGFR and HER2 in response to lapatinib in 61 different human tumor cell lines from 12 tumor types, two oncogene transformed human cell lines, and two normal human cell cultures." (PMID 39239273, 2024). "Given the broad distribution of EGFR expression in many healthy human tissues, EGFR-targeting strategies with improved tumor specificity are required to be able to improve CAR T cell potency without simultaneously enhancing on-target/off-tumor toxicity." (PMID 38492569, 2024). "The accumulation of mutations in different genes, including the epidermal growth factor receptor (EGFR), Kirsten rat sarcoma virus (KRAS), B-Raf proto-oncogene (BRAF), and mesenchymal epithelial transition factor proto-oncogene (MET), leads to uncontrolled cell proliferation and tumor formation." (PMID 39735257, 2024). "CMTM family proteins exert their biological functions by regulating signaling pathways related to cell growth and migration, including the EGFR, WNT, and JAK2/STAT3 signaling pathways, suggesting that CMTM proteins may serve as potential targets for modifying tumor development." (PMID 38223763, 2024). "This ongoing study will further evaluate long-term survival outcome, testifying to the role of tumor-informed MRD detection during the perioperative period and verifying the value of pretreatment immune phenotype in selecting potential beneficiaries of immunotherapy in EGFR-mutant NSCLC." (PMID 38897205, 2024). "However, due to a very strong staining intensity of EGFR in the normal epithelium, a differentiation between healthy and tumor tissue was not always possible (case #11)." (PMID 39406917, 2024). "Here, we evaluated the expression of PD-L1, EGFR, rVAR2, and EpCAM on different NSCLC cell lines and concluded that the combined use of rVAR2 and EpCAM enhances the efficiency of immunomagnetic enrichment for tumor cells with varying levels of target expression." (PMID 39337304, 2024). "However, in CD24−/CD44+‐breast CSCs xenotransplanted group treated with a low dose of doxorubicin and the potent EGFR inhibitor/compound 1e, normal morphology of mammary gland with subcutaneous fat was observed with no tumor mass." (PMID 38522013, 2024). "Similarly, using a novel microfluidic approach, higher levels of EGFR+ EVs were found in the saliva of OSCC patients compared to healthy individuals, and the ratio of Annexin V+ EGFR+ EVs to Annexin V− EGFR+ EVs correlated with the OSCC tumor T stage." (PMID 38610017, 2024). "Proximal C9 cells clustered separately from other tumor cells and showed senescent phenotype, while distal C4 spots exhibited hypermetabolic features and higher activity of oncogenic pathways, such as KRAS and EGFR signaling as well as DAP12 interactions (with myeloid cells)." (PMID 38645221, 2024). "Inhibition of IL-6R, PD-L1 or EGFR resulted in CXCL7 decline, and shCXCL7 decreased MCT-1, IL-6/IL-6R, p-EGFR and PD-L1, which may potentiate therapeutic efficacy against tumor spreading via lymphatic circulation." (PMID 38505617, 2024).
tumor (continued). "In 2020, the FDA declared that patients with unresectable malignant pleural mesothelioma (MPM), and NSCLC (with tumor PD-L1 expression ≥ 1% and without EGFR/ALK alterations) can benefit from treatment with Opdivo (Nivolumab) plus Yervoy (Ipilimumab) as a first-line treatment." (PMID 38391950, 2024). "Furthermore, EGFR staining did not reveal cell membranes, suggesting the degeneration and necrosis of the tumor cells." (PMID 39338408, 2024). "Our investigation reveals that NSCLC cells with EGFR mutations express higher levels of HRS (with no significant change in ALIX) and that the expression level of PD-L1 in circulating sEVs from patients is directly tied to HRS levels in their tumor tissues." (PMID 39062533, 2024). "The authors speculate that the upregulation of STAT3 may mediate the anti-tumor effects of dual HDAC/EGFR inhibition through a tumor-suppressive role, as opposed to its dual action as an oncoprotein." (PMID 38183103, 2024). "Consequently, treatment of SW1990 EGFR-KO or HER2-KO tumors with the ‘tumor monovalent’ EGFRxHER2 T-BsAb failed to confer any therapeutic benefit." (PMID 38650005, 2024). "By targeting tumor cells and the C1 SRSF7+ MCs subtype for interactions analysis, we have identified the secretion of AREG ligands by a subtype of C1 SRSF7+ MCs in the EGF signaling pathway that act on the protein receptor EGFR on the membrane of the tumor cells." (PMID 39430754, 2024). "Furthermore, CD109 induces EGFR-mediated STAT3 phosphorylation, which supports SCC cell migration, proliferation, and the cancer stem cell phenotype in vitro, suggesting its role in enhancing tumor aggressiveness and inflammation." (PMID 39990858, 2024). "Moreover, trial NCT00005813 investigates the use of LAK cells combined with the MDX477 bispecific antibody for intra-tumoral injection in patients with GBM expressing epidermal growth factor receptor (EGFR), aiming to enhance the targeting of tumor cells with bispecific antibodies." (PMID 38732975, 2024). "In three other studies, miR-31 expression was significantly associated with PFS in KRAS wild-type mCRC patients treated with anti-EGFR therapy, but not when the tumour was right-sided, and in these patients, miR-31 was also associated with the time to progression." (PMID 39456841, 2024). "While the tumors were not appreciably larger in the EGFR WT saracatinib-only treated group compared to no treatment control, we found that cells from these tumors invaded beyond the boundary of the tumor into the brain parenchyma to a greater degree than control tumors." (PMID 38892466, 2024). "However, despite GLUT1 being one of the most commonly overexpressed genes related to tumor glycolysis, further exploration of the intrinsic relationship with EGFR is lacking." (PMID 38831321, 2024). "No appreciable lysis of EGFR-negative CT26 tumor cells was detected at any concentration." (PMID 39835115, 2024). "Main weaknesses include lack of tumor genomic characterization (beyond the absence of activating EGFR and ALK alterations), inclusion of only cytotoxic and antiangiogenic therapies, lack of information on postprogression therapy, and exclusion of squamous tumors." (PMID 38207008, 2024). "A newly developed type of nanoparticle targeting EGFR exclusively in an acidic environment may solve the issue of the receptor’s lack of tumor specificity." (PMID 39407936, 2024). "Although clinical studies of EGFR inhibitors across various tumour types have not shown sufficiently high response rates to warrant their use in unselected patients, durable responses have been observed at low frequencies across several epithelial tumour types." (PMID 38605363, 2024). "Successful delivery of the HuR CRISPR plasmid via omSLN-HAR and DTX by omLip-HAR could regulate apoptosis, EGFR, Wnt-activated, MDR, and EMT signaling pathways, and consequently effectively inhibit tumor growth and reduce systemic adverse effects in TNBC in vitro and in vivo." (PMID 39482441, 2024).